MAX (MYC associated transcriptional regulator X)
Diseases named in the same sentence as MAX in open-access papers (continued):
Sharing a sentence is not in itself a finding about the gene and the disease.
polydactyly-macrocephaly syndrome (1 paper, 2024). "GoF mutations in MAX are implicated in polydactyly-macrocephaly syndrome (PDMCS, OMIM#620712), characterized by postaxial polydactyly, progressive macrocephaly, ocular anomalies, and neurodevelopmental issues." (PMID 38884091, 2024). "The GoF MAX variants, the cause of polydactyly-macrocephaly syndrome, are present in the b-HLH-LZ domain, where the mutant MAX binds its target E-box sequence with a lower apparent affinity, leading to a more efficient heterodimerization with Myc and an increase in transcriptional activity of Myc." (PMID 38884091, 2024).
Sepsis (1 paper, 2022). Sepsis is defined as life-threatening organ dysfunction caused by a dysregulated host response to infection. "Furthermore, we analyzed the downstream TFs targeted by LR pairs and found that different TFs, including SMAD3, RBPJ, and MAX, were targeted in sepsis-only patients, while FOS, STAT3, STAT2, and RB1 were targeted in sepsis-induced patients." (PMID 35222683, 2022).
somatotroph tumors (1 paper, 2022). "Germ cell mutations in MAX located at 14q23.3 are associated with neuroendocrine and renal tumors, as well as small-cell lung cancer and both somatotroph tumors and PRLomas." (PMID 36010855, 2022). "While somatic mutations of GNAS are the most prevalent cause of somatotroph tumors, germline mutations in various genes (AIP, PRKAR1A, GPR101, GNAS, MEN1, CDKN1B, SDHx, MAX) are also known as the cause of somatotroph tumors." (PMID 36010855, 2022).
T-cell neoplasms (1 paper, 2020). "From the immunohistochemical results, decreased MAX expression correlated with the expression of cytotoxic molecules such as TIA-1 and granzyme B. Recent reports have shown that expression of cytotoxic molecules may be independent prognostic factors in mature T-cell neoplasms including ALCL21–23." (PMID 32587329, 2020).
tauopathies (1 paper, 2022). "Thus, to discriminate the two tauopathies, we hereby propose JUN(B,D)HIGH, FOS(L1,L2)HIGH as well as the involvement of DUX4, KLF5, MAX::MYC, PAX6, and PPARG to support the identity of CBD-originated astrocytes." (PMID 35976433, 2022).
thymoma (1 paper, 2022). A neoplasm arising from the epithelial cells of the thymus.
tuberous sclerosis syndrome (1 paper, 2025).
tumor (118 papers, 2006 to 2025). "The MYC/MAX/MAD network is a key signaling pathway implicated in tumor proliferation, cell adhesion, and angiogenesis." (PMID 40140670, 2025). "MYC:MAX dimerization is a known critical factor for MYC oncogenesis, as demonstrated in Eμ-Myc-driven lymphomagenesis, where MAX loss results in complete abrogation of tumor development." (PMID 38992040, 2024). "MYC overexpression in tumor cells causes a decrease in the formation of MAX/MAX homodimers, which, in normal conditions, attenuate the binding of MYC to specific (E-boxes) and non-specific DNA sequences." (PMID 36830948, 2023). "MAX variants present with a parent of origin dependent tumorigenesis and tumour formation occurs almost exclusively through paternal transmission." (PMID 33815275, 2021). "Recently, two families with MAX mutations with multiple tumour types were described, including a patient with prolactinoma and parathyroid tumour in one of them." (PMID 33543431, 2021). "This indicates that the MAX R60Q mutation must be present in just a fraction of tumor cells, occurring as a late event." (PMID 34689785, 2021). "All the tumours secreted predominantly norepinephrine, accordingly to the typical biochemical phenotype ascribed to variants in the MAX gene." (PMID 33815275, 2021). "Immunohistochemistry demonstrated loss of MAX protein expression in most tumor cells in PCC of the proband and some Schwannian cells in GN of the proband's son." (PMID 32973681, 2020). "On a similar note, MAX is an oncogene implicated in cell proliferation, differentiation, and apoptosis of certain tumor types." (PMID 33063251, 2020). "In our study, there was a heterozygous pathogenic MAX variant (c.C97T, p.Arg33Ter) in both the peripheral blood and tumor tissues in the GN." (PMID 32973681, 2020). "Nevertheless, immunohistochemistry demonstrated the loss of MAX protein expression in most PCC tumor cells, suggesting a causative role of MAX variants for PCC." (PMID 32973681, 2020). "Overexpression of MYCN allows it to form heterodimers with MYC-associated protein X (MAX) which permits it to act as a transcriptional factor and support continued tumor growth." (PMID 32726962, 2020). "Tumor DNA sequencing showed the same MAX variant (c.C97T, p.Arg33Ter) in PCC of the proband and GN of her son, both with retention of heterozygosity." (PMID 32973681, 2020). "In the present case, we found a same heterozygous pathogenic MAX variant (c.C97T, p.Arg33Ter) in the peripheral blood and tumor tissues of both PCC and GN." (PMID 32973681, 2020). "Genetic analysis of tumor DNA demonstrated that there was a MAX variant (c.C97T, p.Arg33Ter) in PCC of the proband and GN of her son, both with retention of heterozygosity." (PMID 32973681, 2020). "In our study, we have identified a variant of MAX (c.397-2A>G), affecting splice site and pathogenic for the protein function, with the loss of the wild-type allele in the tumor as second hit." (PMID 30211214, 2018). "Here the authors find mutations resulting in loss of MAX protein expression conserved between primary tumours and metastases in the same patients, suggesting that MAX mutation is an early event." (PMID 28270683, 2017). "We detected hemizygous and homozygous MAX-inactivating mutations in 21% of the 76 GISTs in this study, thereby demonstrating that GIST is the neoplasia with the highest known frequency of MAX tumour suppressor mutations." (PMID 28270683, 2017). "WES analysis also identified a truncating frameshift mutation (c.160delC; p.Gln54Lysfs*10) in exon 3 of the MYC-associated factor (MAX) gene in the tumor DNA." (PMID 26555092, 2015). "Exceptionally, PGL may be the tumor arising from chromaffin cells in CP as recently documented in a case with MAX germline mutation and retroperitoneal PGL diagnosed at 20 years old followed by unilateral multifocal PCC at 28 years old." (PMID 36187102, 2022). "DNA extracted from frozen tumor tissues of the proband and her son underwent MAX mutation analysis." (PMID 32973681, 2020).
tumor (continued). "However, we identified a nonsense mutation in MGA (p.Glu210*), a tumor suppressor gene that interacts with MAX, only in the NB15 relapse tumor." (PMID 28915622, 2017). "Thus NF1, VHL, RET, and MAX germline and somatic mutations have been reported in 3–25%, 13–9%, 5–5%, and 1–3% of tumours, respectively." (PMID 25883647, 2015). "Consequently, inhibition of MYC-dependent cell transformation by MAX protein is disrupted, causing tumor development." (PMID 24899893, 2014). "Although MAX acts as a tumor suppressor in small cell lung cancer, it can also interact with NF-κB synergistically to promote Fas ligand expression in NSCLC and promote Fas related immune escape mechanism." (PMID 38372784, 2024). "Consistently, PCNA staining is highest for tumor overexpressing MAX, and the opposite is true for MAX knockdown (bottom)." (PMID 37347224, 2023). "CCA cells overexpressing MAX resulted in much larger tumor sizes as compared with respective controls." (PMID 37347224, 2023). "The development of small molecule inhibitors that disrupt MYC/MAX heterodimerization further emphasized the importance of promoting MYC degradation to suppress tumor growth and enhance immunotherapy." (PMID 37400551, 2023). "MXD4 is a MAD family protein and putative tumor suppressor that, through heterodimerization with MAX, antagonizes MYC and downstream gene regulatory activities." (PMID 37894362, 2023). "An intraperitoneal injection of either MT-1 or in combination with 3jc48-3, an inhibitor of obligate heterodimerization with MYC-associated protein X (MAX), in mice implanted with orthotopic PC PDX, decreased tumor growth." (PMID 37568667, 2023). "TF factor motif analysis within H3K27ac peaks revealed 29 MG63-specific TF binding sites, including those for EOMES, PRDM1, EPAS1 (HIF2A), E2F6, and MYC/MAX, which reflect known early development, tumor-initiation, and stemness factors (Worksheet 1)." (PMID 37228489, 2023). "TFs, such as XBP1, TAF7, ELF3, MYC, MAX, etc., were more enriched in tumor cells of luminal BC than the other two subtypes." (PMID 36077333, 2022). "We found that XBP1, TAF7, ELF3, MYC, MAX, etc., were more enriched in tumor cells of luminal BC than the other two subtypes." (PMID 36077333, 2022). "Surprisingly, clusters with the strongest oncogenic and tumour suppressor potential share five regulatory regions (MAX, ERG, EP300, AR and MYC)." (PMID 34198662, 2021). "The regressive tumor WT01 carried GLI3 Q1437*, the triphasic WT02 harbored MAX R60Q and MYCN T58M mutations, and the blastemal WT03 showed a heterozygous DIS3L2 deletion and a STK32C V339M mutation." (PMID 31562394, 2020). "Immunohistochemical detection of MAX showed that most tumor cells in PCC of the proband were negatively stained, but some tumor cells were positive." (PMID 32973681, 2020). "Since MAX behaves as a TSG, we analyzed the tumor DNAs of patient III-3 and identified loss of the MAX WT allele in both tumors suggesting that this variant is indeed responsible for the bilateral PCC in this patient." (PMID 33112832, 2020). "YY1/MAX expression in the tumor bulk and surrounding normal tissue was variable without any particular correspondence with the invasive subtype of the tumor." (PMID 33063251, 2020). "Immunohistochemical staining was performed using 3-μm formalin-fixed paraffin-embedded tumor sections from the proband's PCC and her son's GN, which carry MAX variants." (PMID 32973681, 2020). "MAX-independent expression of MYC in MM and its precursors requires further investigation; a recent abstract identified MAX as a tumor suppressor driver gene in MM, which is a promising start." (PMID 31156714, 2019). "Inhibition of tumor cell growth in vivo using mouse tumor models has been reported previously for the MYC:MAX inhibitors 10058-F4, KJ-Pyr-9, KSI-3716 and Mycro327,28,61,62." (PMID 29968736, 2018).
tumor (continued). "It includes oncogenes—rearranged during transfection (RET) proto-oncogene and H-ras GTPase proto-oncogene (HRAS)—and several tumor suppressors: neurofibromin 1 (NF1), transmembrane protein 127 (TMEM127), and MYC-associated factor X (MAX)." (PMID 30345003, 2018). "It has been also demonstrated that the normal function of this tumor suppressor miRNA is to down-regulate a number of putative oncogenes including validated miR-22 targets MAX, MYCBP, HDAC4, HDAC6, CDK6, CDKN1A and NCoA1." (PMID 29716630, 2018). "In other words, deregulated MYC can bind MAX and alter normal ongoing gene expression programs to impose a tumor-specific transcription profile." (PMID 30054853, 2018). "Altogether, our studies demonstrate frequent disruption of MAX tumour suppressive roles during early progression of KIT-mutant, PDGFRA-mutant and NF1-mutant GISTs." (PMID 28270683, 2017). "Considering the location of the tumour; intra-adrenal tumours suggest possible RET, VHL, NF1, TMEM 127, MAX or rarely KIF1B mutations." (PMID 29166454, 2017). "More recently, integrative genomic approaches identified germline mutations in two new tumour suppressor genes: TMEM127 and MAX genes which predispose to familial, bilateral, or apparently sporadic PCCs." (PMID 28471419, 2017). "The second cluster contained the kinase signalling subgroup including the RET, NF1, TMEM 127 and MAX mutant tumours." (PMID 29166454, 2017). "At the genomic level, gains of MYC locus and losses of MAX (Myc-associated factor X), a negative regulator of MYC18, were more frequent in O1 than in O2 and O3 tumours (t-test P values=0.02 and 0.0002, respectively)." (PMID 27090007, 2016). "We further demonstrate that normal function of this tumor suppressor microRNA is to down-regulate a number of putative oncogenes including validated miR-22 targets MAX, MYCBP, HDAC4, HDAC6, CDK6, and NCoA1." (PMID 26244872, 2015). "We have found evidences that MAX is one of the master regulators of tumor progression, possibly by being an additional regulatory step for the availability of MYC:MAX heterodimers to regulate transcription and increase proliferation." (PMID 24349289, 2013). "c-myc is an oncogene that codes for transcription factor Myc that along with other binding partners such as MAX plays an important role widely studied in various physiological processes including tumor growth in different cancers." (PMID 17217525, 2006). "Mutation features, such as microsatellite instability (MSI), tumor mutational burden (TMB), and mutations in pathways like MYC-associated factor X (MAX), which are commonly used to assess the efficacy of clinical immunotherapy, do not show significant differences among subtypes." (PMID 41400463, 2025). "Partly due to physiological adrenal uptake of 68Ga-DOTA-SSA PET/CT, more tumor specific 18F-FDOPA PET/CT may be preferred in PCCs that are small and/or related to known mutations in NF1, RET, VHL, or MAX." (PMID 38206185, 2024). "Tumors were considered MAX-positive if MAX was expressed in the nucleus of >30% of tumor cells." (PMID 36352191, 2023). "In contrast, CCA cells overexpressing CRISPR targeting MAX had much smaller tumor sizes." (PMID 37347224, 2023). "Moreover, our in vivo study demonstrated that tumor growth and metastatic potential of Hepa1–6 cells was significantly repressed by MAX or CCL5 depletion in immune-competent mice in comparison to that of the vector control." (PMID 34215748, 2021). "This difference of MAX expression in ALK-positive ALCL between the datasets may be attributed to the percentage of tumor cells in each sample." (PMID 32587329, 2020). "It is consistent with some tumor cells in PCC which were positive for MAX immunostaining." (PMID 32973681, 2020).
tumor (continued). "In CRC, a MAX/MYC heterodimer induced by elevated HIF-2α mediates transcriptional repression of hypoxia-related miR-15-16, leading to tumor angiogenesis and hematogenous metastasis by further loss of post-transcriptional restriction towards fibroblast growth factor-2." (PMID 32102656, 2020). "CDKs and tyrosine protein kinase JAK2 act as cellular oncoproteins and MAX as a tumor suppressor." (PMID 31803618, 2019). "In addition, somatic mutations in the previously known genes VHL, RET, MAX, and HRAS were found in one tumor each, in agreement with frequencies in previous reports." (PMID 29159601, 2018). "MAX also interacts with a group of transcriptional repressors which can antagonize the transcriptional activity of MYC-MAX complexes and may therefore function as tumor suppressors." (PMID 28230739, 2017). "In addition, mutations in patients with PCCs have recently been described in TMEM127, which is a negative regulator of the mTOR pathway and MAX, the MYC-associated factor X gene, which is a tumor suppressor." (PMID 22323007, 2012). "This raises the possibility that MAX may also be limiting in tumours where c-MYC levels are very high." (PMID 18493233, 2008). "Increased MAX expression has been linked to increased proliferation, but the mechanism by which MAX overexpression may occur in tumours is elusive." (PMID 18493233, 2008). "The second cluster group comprises tumours caused by mutations in the neurofibromatosis type 1 (NF1) tumour suppressor gene, the rearranged during transfection (RET) proto-oncogene, the transmembrane protein 127 (TMEM127) gene and the MYC-associated factor X (MAX) gene." (PMID 40540150, 2025). "Although the MAX mutation is classified as type C2, including RET, NF1, TMEM127,H-RAS and ATRX, which belongs to the SWI/SNF family of chromatin remodeling proteins, as their upregulation will activate the PI3K/AKT and RAS/MAPK signaling pathways resulting in tumor formation." (PMID 39279998, 2024). "MAX behaves as a classical tumour suppressor gene that encodes for the MAX protein, which interacts with the MYC proto-oncogene and the MAX dimerization protein 1 (MXD1) family of proteins; this MYC/MAX/MXD1 network regulates cell proliferation, differentiation and apoptosis." (PMID 33815275, 2021). "Lastly, we have observed that MAX expression was significantly altered during SH-SY5Y retinoic acid-induced differentiation, providing a mechanism for which this gene could be linked to tumor progression." (PMID 24349289, 2013). "Interestingly, the authors noted that the MAX transgene with higher activity presented more pronounced tumor impairing capacity than the less active one, indicating that MAX has indeed tumor suppressing properties, and that the latter may be dose-dependent." (PMID 24349289, 2013). "The compound KI-MS2-008 stabilizes the MAX–MAX homodimers to decrease the expression of MYC target genes and decreases tumor growth in vivo." (PMID 40290126, 2025). "The small molecule MYC inhibitor (MYCi975) that disrupts MYC/MAX dimers and induces MYC degradation in diverse tumor cell lines likewise reduced cell viability of WT cultures, with organoids being most sensitive." (PMID 39740515, 2025). "The regulon specificity score (RSS) highlighted unique regulons across the three studied regions, with MITF(+), PRDM1(+), MAX(+), TFEC(+), and BHLHE41(+) emerging as the most specific regulons within the tumor core." (PMID 38938448, 2024).